HPSE (heparanase)
Diseases named in the same sentence as HPSE in open-access papers (continued):
Sharing a sentence is not in itself a finding about the gene and the disease.
glioblastoma (8 papers, 2012 to 2025). The most malignant astrocytic tumor (WHO grade IV). "Immunohistochemistry IHC analysis has revealed low levels of HPSE in normal brain tissue and elevated levels in Grades II and IV; high HPSE expression in patients with glioblastoma was found to be associated with shorter survival." (PMID 32075104, 2020). "Low levels of HPSE in normal brain tissue and elevated levels in Grades II and IV were demonstrated by IHC; high HPSE expression in patients with glioblastoma was found to be associated with shorter survival." (PMID 32075104, 2020). "In glioblastoma, glioma-associated oncogene homolog 1 facilitates the transcription of HPSE to promote tumor angiogenesis and aggressive growth." (PMID 27595937, 2016). "The specificity of αHS for HS was also true in vivo in glioblastoma xenograft tumor sections, as heparanase treatment resulted in a complete loss of αHS staining." (PMID 23152853, 2012). "It indicates a role for HPSE inhibitors in the balance between apoptosis and autophagy in U87 human glioblastoma cells, suggesting a potential role for this new class of compounds in the control of tumor growth progression." (PMID 37508554, 2023). "The expression of HS biosynthetic enzymes, including HS6ST1–3, has been shown to be predominantly down-regulated in glioblastoma, with the striking exceptions of HS3ST3a1 and the extracellular HS modifying enzyme HPSE." (PMID 29104277, 2017). "In human U87 glioblastoma cell lines, an increase in heparanase expression also enhances the invasive potential of cells, but reduces their proliferative activity, facilitates cell spreading and monolayer formation." (PMID 29104277, 2017). "Although a decreased HPSE expression was detected at the mRNA level, immunohistochemical analysis demonstrated the presence of HPSE protein molecules in 50% of the studied glioblastoma tumours." (PMID 29104277, 2017). "By interfering with the autophagic flux and promoting apoptosis, heparanase inhibitors may enhance the sensitivity of glioblastoma cells to therapeutic agents, providing a promising approach for treatment strategies (Carolyn G and Renato V, 2022)." (PMID 40171042, 2025). "To assess whether the suppression of autophagic flux upon RDS 3337 treatment can activate cytotoxic mechanisms in U87 human glioblastoma cells, we investigated cell death rates following treatment with the HPSE inhibitor." (PMID 37508554, 2023). "It has been previously shown that HPSE mRNA is increased in oligodendroglioma (Grade II), anaplastic astrocytoma (Grade III) and glioblastoma (Grade IV) compared with normal brain tissue; Western blot has demonstrated the increase of HPSE protein in anaplastic astrocytoma and glioblastoma." (PMID 32075104, 2020). "The heterogeneous expression of heparanase in individual glioblastoma tumours might contribute to the HS content in these tissues and structure of the tumour microenvironment." (PMID 29104277, 2017). "Moreover, recent studies have suggested that inhibiting heparanase, an enzyme involved in the remodeling of the extracellular matrix, may significantly affect the regulation of autophagy and apoptosis in glioblastoma." (PMID 40171042, 2025). "In this research, we investigated the role of a new HPSE inhibitor, RDS 3337, in the regulation of the autophagic process and the balance between apoptosis and autophagy in U87 glioblastoma cells." (PMID 37508554, 2023). "In this research, we investigated the role of the HPSE inhibitor RDS 3337 (7 g) in the regulation of the autophagic process and the balance between apoptosis and autophagy in U87 human glioblastoma cells." (PMID 37508554, 2023). "Interestingly, in addition to the heterogeneity of individual glioblastoma tumours for the presence/absence of HPSE expression, a high intratumoural heterogeneity of anti-HPSE staining was revealed in HPSE-positive ones." (PMID 29104277, 2017).
glioblastoma (continued). "The immunohistochemical analysis (IHC) was performed for glioblastoma (Grade IV) tissues only, and no staining for the HPSE protein molecule was shown for a near a half of the analysed GBM tumours, while the other 50% of the GBM tumours demonstrated positive signal for HPSE protein." (PMID 29104277, 2017).
inflammatory bowel disease (8 papers, 2011 to 2022). A spectrum of small and large bowel inflammatory diseases of unknown etiology. "In addition, increased HPSE expression in epithelium has been associated with inflammation and inflammation-associated tumorigenesis, such as inflammatory bowel disease (IBD), pancreatitis, and esophageal carcinoma." (PMID 34461608, 2021). "HPSE expression is induced in all major types of human cancer, is often associated with reduced patient survival and increased tumor metastasis, and has been shown to be associated with numerous inflammatory conditions, such as inflammatory bowel disease and rheumatoid arthritis." (PMID 29379222, 2017). "The link of heparanase to inflammatory bowel disease is based on results obtained in a mouse model over-expressing heparanase, in which the inflammatory profile of macrophages was preserved for more than a month after termination of the pro-inflammatory DSS treatment." (PMID 24465803, 2014). "This was identified in patients with inflammatory bowel disease (IBD), and in an IBD model, epithelial cell-heparanase was found to drive the over-activation of macrophages, inflammation, and ultimately tumorigenesis." (PMID 31110966, 2019).
metastatic tumors (8 papers, 2005 to 2022). "Seventy samples were stained negative or weak (+1) for heparanase, of which 28 (40%) developed metastatic disease." (PMID 29464068, 2018). "Furthermore, metastatic tumors showed greater variability in their levels of transcription, HPSE mRNA values appearing reduced in 40 % of patients, at the same time as 20 % of patients showing overexpression, results which combined to produce the lack of a statistically significant trend (p = 0.13)." (PMID 26482785, 2015). "The overexpression of HPSE in metastatic tumors has been widely referenced in the literature, although our results show that it did not appear to undergo changes in levels of transcription, although its protein levels could well be controlled by a more stable mRNA isoform." (PMID 23327652, 2013). "Strong heparanase staining in the primary tumor of the entire cohort was not a prognostic factor for metastatic disease." (PMID 29464068, 2018). "However, the pro-metastatic enzyme heparanase did not exhibit significant changes in mRNA expression, although in metastatic tumors it appeared related to increased levels of the most stable form of mRNA." (PMID 23327652, 2013).
thrombosis (8 papers, 2012 to 2026). "Heparanase procoagulant activity was higher than 31 ng/mL in the four cases of thrombosis detected during the follow-up period." (PMID 25386347, 2014).
type 1 diabetes (8 papers, 2014 to 2022). "A study focused on type 1 diabetes (T1D) in mouse models suggests that pancreatic islets, containing insulin-secreting β-cells, are susceptible to damage by heparanase and the inhibition of heparanase could be protective for T1D22." (PMID 29079728, 2017). "Heparanase assists leukocyte migration across basement membranes by acting as a “path-maker”; however, in type 1 diabetes Hpse activity actually drives the disease process." (PMID 26136747, 2015). "Indeed, pioneering studies by C R. Parish and his group identified multiple roles for heparanase in islet damage (originally—in the setting of type 1 diabetes)." (PMID 31921662, 2019).
type 2 diabetes (8 papers, 2009 to 2024). "The recent studies showed that increased plasma heparanase levels were found in type 2 diabetic patients and urine heparanase was associated with elevated blood glucose levels." (PMID 28994624, 2017). "Whether and how HPSE regulates glomerular EndMT in type 2 diabetes may help us to further understand the roles of HPSE in the process of EndMT of GEnCs." (PMID 35173145, 2022).
cervical carcinoma (7 papers, 2012 to 2024). A carcinoma arising from either the exocervical squamous epithelium or the endocervical glandular epithelium. "For this purpose, cervical carcinoma cells (SiHa) were left untreated (Con) or were incubated with latent 65 kDa heparanase (1 ug/mL) together with increasing concentrations (1, 5, 10 ug/mL) of compound XII." (PMID 38334603, 2024). "Here, we investigated heparanase (HPA), which plays an important role in cervical cancer metastasis and angiogenesis, as a molecular target for cervical cancer treatment." (PMID 27166252, 2016). "Ectopic heparanase overexpression can promote proliferation of cervical cancers in vitro and tumor growth in vivo." (PMID 26052253, 2015). "During the past decade, many clinical data have revealed that the overexpression of HPSE correlates with reduced postoperative survival and poorer prognosis of colorectal, pancreatic, bladder, gastric, and cervical cancer patients." (PMID 22719918, 2012). "Immunohistochemical positivity for heparanase was 63.3% (38/60) in cervical cancer patients." (PMID 26052253, 2015).
leukemia (7 papers, 2008 to 2021). A malignant (clonal) hematologic disorder, involving hematopoietic stem cells and characterized by the presence of primitive or atypical myeloid or lymphoid cells in the bone marrow and the blood. "Our results revealed that in malignant cell lines and primary leukemia samples, heparanase discontinues self-regulation of the enhancer region." (PMID 29955035, 2018). "Rac1 activation was markedly induced following heparanase addition to ARF-77 leukemia F cells (Hepa)." (PMID 18545691, 2008). "In contrast, heparanase appeared more efficient in stimulating the adhesion of floating ARH-77 leukemia cells compared with the KKDC peptide." (PMID 18545691, 2008). "Importantly, we found that heparanase potentiates the bioactivity of resistin in its standard bioassay in which monocytic human leukemia cell line, THP1, differentiates into adherent macrophage-like foam cells." (PMID 24465803, 2014).
liver cancer (7 papers, 2012 to 2024). An epithelial or non-epithelial malignant neoplasm that arises from the liver. "It should be mentioned here that HPSE protein was located in both the cytoplasm and nucleus of liver cancer cell in the present study, and the protein in the nucleus was reported to be favorable to the outcome of cancer." (PMID 22952874, 2012). "Since a recent study showed that PPARɣ regulates HPSE expression in liver cancer cells, we hypothesized that PPARɣ agonists exert their reno-protective effect by inhibiting glomerular HPSE expression." (PMID 36889064, 2023). "Interestingly, HPSE protein was detected in both the cytoplasm and nucleus of liver cancer cell, which is in sharp contrast to previous studies that found HPSE protein exclusively in either the cytoplasm or nucleus of cancer cells." (PMID 22952874, 2012). "We hypothesized that PPARɣ agonists exert their renoprotective effect by inhibiting the expression of glomerular HPSE since HPSE is essential for the development of proteinuria, TZDs reduce proteinuria, and PPARɣ regulates HPSE expression in liver cancer cells." (PMID 36889064, 2023). "Twoanti-heparanase antibodies (multiple antigenic peptides MAP1 and MAP2) caneffectively inhibit the heparanase activity of HCCLM6 liver cancer cells, therebyinfluencing their invasive capacity (Yang etal., 2009)." (PMID 28981558, 2017).
neuroblastoma (7 papers, 2016 to 2025). Neuroblastoma (NB) is the most common solid, extracranial childhood tumor. "Heparanase (HPSE), as an endogenous endoglycosidase, is highly expressed in high-risk neuroblastoma." (PMID 35643506, 2022). "By engineering GD2-directed CAR T cells to co-express heparanase, they achieved enhanced infiltration and anti-tumor activity in a neuroblastoma model." (PMID 40517137, 2025). "Heparanase (HPSE) is the only endo-β-D-glucuronidase that is correlated with the progression of neuroblastoma (NB), the most common extracranial malignancy in childhood." (PMID 27595937, 2016). "For instance, GD2-targeted CAR T cells engineered with heparanase (HPSE), an enzyme which degrades HSPGs of the ECM, have been shown to improve infiltration and anti-tumor function in a xenograft mouse model of human neuroblastoma." (PMID 32570906, 2020).
renal fibrosis (7 papers, 2015 to 2021). A final common manifestation of a wide variety of chronic kidney diseases characterized by glomerulosclerosis and tubulointerstitial fibrosis. "EMT associated with hypersecretion of heparanase (HPSE) was reported in renal fibrosis." (PMID 30333909, 2018). "Heparanase is an active player in glycocalyx remodeling, and the same agents that disrupt glycocalyx represent an element of damage and triggers renal fibrosis." (PMID 33804258, 2021). "The present study points out that HPSE is actively involved in the mechanisms that regulate the development of renal fibrosis arising in the transplanted organ as a consequence of ischemia/reperfusion damage." (PMID 30546836, 2018). "Important evidence of the utility of anti-HPSE therapies to control the progression of renal fibrosis comes from both in vitro and in vivo studies." (PMID 26040666, 2015). "Likewise, heparanase has been shown to play a key role in renal fibrosis by regulating TGF‐β expression and activity." (PMID 28286736, 2017). "Second, using gene silencing approaches we further revealed an essential involvement of heparanase in the development of I/R-induced epithelial damage and suggested that its inhibition may signify a therapeutic approach to minimize/prevent ischemic-induced renal fibrosis." (PMID 28388547, 2017). "Heparanase was found to regulate TGF‐β expression and activity in renal fibrosis, proposing a role of heparanase in the axis of HS structure and TGF‐β activity." (PMID 28286736, 2017).
acute kidney injury (6 papers, 2013 to 2023). Sudden and sustained deterioration of the kidney function characterized by decreased glomerular filtration rate, increased serum creatinine or oliguria. "In conclusion, this study demonstrated that XSF ameliorated STZ-induced renal failure through inhibiting arginase activity and heparanase protein expression in GECs contributes to the therapeutic effect of XSF." (PMID 30319431, 2018). "Heparanase is known mammalian endoglycosidase that cleaves heparin sulfate (HS) and finally results in the progression of proteinuria and renal failure." (PMID 30319431, 2018).
Autoimmunity (6 papers, 2011 to 2025). The occurrence of an immune reaction against the organism's own cells or tissues. "Heparanase activity is also implicated in neovascularization, inflammation, and autoimmunity, involving migration of vascular endothelial cells and activated cells of the immune system." (PMID 23908791, 2011). "Thus, it appears that both heparanase and resistin may play a common and co-operative role in inflammation and autoimmunity." (PMID 24465803, 2014). "Together, these data identify a role for HPSE and the ECM in immune tolerance, providing new avenues for improving Treg-based therapy of autoimmunity." (PMID 38378682, 2024). "Notably, heparanase staining was primarily detected in epithelial rather than immune cells, indicating that heparanase levels are elevated under chronic inflammatory conditions and autoimmunity." (PMID 23908791, 2011).
colorectal cancer (6 papers, 2015 to 2025). A primary or metastatic malignant neoplasm that affects the colon or rectum. "In this study, we examined the expression of HPSE in different colorectal cancer (CRC) cell lines." (PMID 31001480, 2019). "Likewise, HPSE2 was suggested as a good tumor marker, better than HPSE, for the first time only in 2008 in colorectal carcinoma in comparison with normal mucosa with sensitivity of 98% and specificity of 100% using immunohistochemistry technique." (PMID 26488476, 2015). "This analysis identified five glycosyltransferase genes, namely, ST6GAL1, GALNT6, HPSE, GALNT1, and GALNT7, expression of which was consistently upregulated or downregulated in MSI colorectal cancer tissues, cell lines, and single epithelial cells compared with MSS colorectal cancers." (PMID 40824763, 2025).
ischemic stroke (6 papers, 2012 to 2023). A stroke disorder caused by obstruction of blood flow to the brain, due to thrombotic (local blood clot formation) or embolic (due to a blood clot or other material traveling from another site) event. "Heparanase, a mammalian endo-β-D-glucoronidase that specifically degrades heparan sulfate, has been implicated in inflammation and ischemic stroke." (PMID 28720149, 2017). "This is in line with other studies showing that heparanase is upregulated in ischemic stroke, expressed in reactive astrocytes and involved in neuroinflammation." (PMID 38107409, 2023). "A few reports have demonstrated that heparanase is upregulated in the rat brain after ischemic stroke." (PMID 28720149, 2017). "Therefore, HPSE inhibitor, especially anti-heparanase mAbs currently developed for cancer, might exert more protective effects on the glycocalyx during the acute phase of ischemic stroke." (PMID 33127645, 2020). "Glycocalyx dysfunction, due to HPSE or MMP9, in several diseases and increased levels of HYAL1 and 2 in infarct lesions of ischemic stroke patients were reported." (PMID 33127645, 2020).
lymph node metastasis (6 papers, 2012 to 2019). "Our data showed that the high levels of salivary heparanase were associated with increased lymph node metastasis (P = 0.0235) and poorer TNM stage (P = 0.0183)." (PMID 26569485, 2015). "High salivary heparanase levels were positively correlated with increased lymph node metastasis (P = 0.0235) and poorer tumor node metastasis stage (TNM) (P = 0.0183)." (PMID 26569485, 2015).
metastatic cancer (6 papers, 2012 to 2025). A carcinoma which has spread from the original site of growth to another anatomic site. "As platelets play important roles in tumor metastasis, these findings indicate contribution of the platelet heparanase to hyper-thrombotic conditions often seen in patients with metastatic cancer." (PMID 27129145, 2016). "Since platelets play pivotal roles in cancer metastasis, this newly ascribed function of heparanase in platelets provides significant insight for clinical management of metastatic cancer." (PMID 27129145, 2016).
Obesity (6 papers, 2012 to 2022). Accumulation of substantial excess body fat. "The results indicate that heparanase inhibits obesity by degrading HS chains, presumably linked to syndecan-3, thereby suppressing the binding of AgRP to MC4R." (PMID 22479599, 2012). "Here, utilizing in vitro and in vivo models of BC, we show that macrophages, whose adverse activation by obesogenic substances is fueled by heparanase (extracellular matrix-degrading enzyme), are capable of upregulating ER expression in tumor cells, in the setting of obesity-associated BC." (PMID 36139419, 2022). "Of note, heparanase was recently shown to sustain Mφ reactivity in several obesity-related and unrelated, Mφ-driven inflammatory conditions." (PMID 36139419, 2022). "By contrast, heparanase knockout mice on a high-fat diet showed increased food intake and maturity-onset obesity, with up to a 40% increase in body fat." (PMID 22479599, 2012). "Interestingly, in mice deficient for heparanase, an endoglucuronidase that cleaves heparan sulfate in ECM, the acceleration of tumor progression in diet-induced obesity was abolished." (PMID 36074318, 2022). "First, utilizing the obesity-associated E0771 BC model in heparanase-null Hpse-KO mice, we found that, unlike in wild-type (wt) animals, the obese state failed to upregulate ERα expression in BC tumors under conditions of heparanase deficiency." (PMID 36139419, 2022).